ERBB2 (erb-b2 receptor tyrosine kinase 2)
Diseases named in the same sentence as ERBB2 in open-access papers (continued):
Sharing a sentence is not in itself a finding about the gene and the disease.
adenocarcinoma (379 papers, 1998 to 2026). A common cancer characterized by the presence of malignant glandular cells. "Overexpression of wild-type human ERBB2 in mouse lungs was shown to cause the development of adenocarcinoma." (PMID 31248101, 2019). "Aberrations in ERBB2 were found only in patients with adenocarcinoma, NOS (7/46 patients [15.2%] [two mutations and five amplifications])." (PMID 26247885, 2015). "In a previous report, including 20 adenocarcinomas, a significant association was found between the expression of erbB-2 and pAkt." (PMID 11870534, 2002). "New therapeutic strategies are now being developed against adenocarcinoma associated with erbB-2 amplification, particularly by inhibiting p185erbB-2 expression." (PMID 9652760, 1998). "However, prolonged survival has been reported in patients with symptomatic bone marrow metastasis from EGFR‐, ERBB2‐ mutated or ALK fusion—positive adenocarcinoma treated with tyrosine kinase inhibitors." (PMID 41314797, 2025). "By contrast, ERBB2 mutations were reduced in CCNE1-amplified EG adenocarcinoma." (PMID 38717153, 2024). "Notably, high expression of either ERBB2 or ERBB3 is associated with resistance of adenocarcinoma to chemotherapy, although these data should be interpreted with caution due to the low sample sizes available." (PMID 31032816, 2019). "Lung biopsy confirmed TTF-1 and Napsin A-positive adenocarcinoma, and genomic profiling identified an ERBB2 (HER2) exon 20 insertion mutation (p.A775_G776insYVMA; VAF 3.9%)." (PMID 42058342, 2026). "HER2 (ERBB2) gene alterations, such as mutations and amplifications, are identified in approximately 2–4% of NSCLC cases, predominantly among adenocarcinoma cases." (PMID 41256321, 2025). "HER2 (ERBB2) amplification or overexpression is observed in approximately 15–20% of advanced gastric or gastroesophageal junction (GEJ) adenocarcinomas." (PMID 41020040, 2025). "All 18 EGFR/ERBB2 ex20 ins/dup-positive cases were adenocarcinomas and most frequently had the acinar predominant growth pattern (64%, n = 11)." (PMID 37284196, 2023). "Second, according to the guidelines for BC, ERBB2 immunoscoring provides lower frequencies for scores of 2+ and 3+ than the validated scoring system for adenocarcinomas of the stomach or gastroesophageal junction." (PMID 37173881, 2023). "Pathology for 24 patients (92.3%) revealed adenocarcinoma and 9 patients (34.6%) had additional mutations in actionable driver mutations (EGFR, ALK, BRAF, MET or ERBB2)." (PMID 37835426, 2023). "Pathology for 25 patients (96.2%) in the wt-BRCA group revealed adenocarcinoma and 9 patients (34.6%) had additional mutations in actionable driver mutations (EGFR, ALK, BRAF, MET or ERBB2)." (PMID 37835426, 2023). "EBVaGCs with intestinal histology were frequently accompanied by genetic alterations, which were known to frequently occur in conventional intestinal-type adenocarcinoma, including KRAS, FBXW7, MUC6, ERBB2, CTNNB1, and ERBB2 amplification mutations." (PMID 37945587, 2023). "Lastly, there was a trend toward more patients with adenocarcinoma harboring ERBB2 alterations (27.3% vs 4.8%, p=0.07)." (PMID 34011535, 2021). "With the progression of the disease, mutations of EGFR L858R, PIK3CA H1047R, and ERBB2 S310F were detected in punctured lumbar tissues, and EGFR L858R and PIK3CA H1047R in ctDNA, consistent with the pathological characteristics of adenocarcinoma." (PMID 32508051, 2020). "The HER2 (official name is ERBB2) gene encodes a membrane receptor in the epidermal growth factor receptor family amplified and over expressed in adenocarcinoma." (PMID 31888619, 2019).
adenocarcinoma (continued). "The fusion gene has been observed predominantly in adenocarcinomas (4–7%) and is mutually exclusive with mutations in the EGFR, K-ras, and ERBB2 genes." (PMID 22363766, 2012). "In particular, we found that an erbB2 CN >2 was correlated to a worst survival rate in the adenocarcinoma histotype." (PMID 21481261, 2011). "In this case of adenocarcinoma of the gastroesophageal junction, we examined the erbB2 expression in multiple metastatic lesions as well as the interlesional heterogeneity in response to chemotherapy." (PMID 22014070, 2011). "Here, erbB2 CN variations were significantly correlated to the survival rates of the adenocarcinoma cases (P = 0.03)." (PMID 21481261, 2011). "Overexpression of wild-type murine homologue of ERBB2 (neu) or activated neu leads to focal adenocarcinoma after long latency or multifocal adenocarcinoma with a shorter latency, respectively." (PMID 20010942, 2010). "Previous studies have shown that similar to other EGFR variants, EGFR/ERBB2 ex20 ins/dup is predominantly found in adenocarcinoma, non-smokers, and women." (PMID 37284196, 2023). "A whole genome sequencing (WGS) analysis revealed that the squamous cell carcinoma lesion and the adenocarcinoma lesion shared genetic patterns such as ERBB2-amplification and integration of the human papilloma virus 16 (HPV-16) genome and that they originated from common ancestor cells." (PMID 39516338, 2023). "Finally, ERBB2 was amplified in all the components of one ITPN sample with concomitant adenocarcinoma." (PMID 36056133, 2022). "Pparγ1 should be considered further for coextinction paradigms in ErbB2-mediated adenocarcinoma." (PMID 33946495, 2021). "Endogenous Pparγ1 enhanced EphA2 mRNA and protein abundance in the ErbB2 adenocarcinoma." (PMID 33946495, 2021). "Moreover, we also observed concurrent mutations of EGFR L858R and ERBB2 S310F in two adenocarcinoma patients; EGFR L858R and ERBB2 amplification in three LUAD patients." (PMID 31692283, 2020). "Interestingly, the mutant KRAS-driven GBCs predominantly led to adenocarcinomas with tubular structures whereas the ERBB2-driven GBC frequently showed a pronounced tubulo-papillary/papillary differentiation." (PMID 31795490, 2019). "Adenocarcinoma cases had a higher prevalence of SNVs, CNVs, and/or fusions/rearrangements in 28 genes including therapy-associated genes such as KRAS (37.5% vs 4.6%), EGFR (17.1% vs 1.3%), BRAF (5.2% vs 1%), ERBB2 (1.8% vs 0.8%), RET (0.9% vs 0.3%), and ROS1 (1.2% vs 0.1%)." (PMID 39664186, 2024). "Overexpression of ERBB2, a marker of highly aggressive tumors, is observed in 20-23% of G/GEJ adenocarcinomas." (PMID 35463314, 2022). "Several of the identified mGISTIC regions harbored known or putative adenocarcinoma driver candidates, such as EGFR, MDM2, KRAS, MYC, TERT, MET, CCND1, NKX2-1/TITF1, CDK4, ERBB2, ID1, RB1, CDKN2A and PTEN." (PMID 24205279, 2013).
adenocarcinoma (continued). "A 39-year-old woman diagnosed with Stage IV adenocarcinoma of the left lung, negative for EGFR, ALK, and ROS-1, but with an ERBB2 mutation, experienced neurological symptoms leading to a diagnosis of brain metastasis in 2019." (PMID 41180730, 2025). "A 39-year-old woman was diagnosed with Stage IV adenocarcinoma of the left lung, which tested negative for EGFR, ALK, and ROS-1 mutations, while showing a 2% expression of PD-L1 and an ERBB2 mutation." (PMID 41180730, 2025). "Consequently, the gene silencing and/or drug‐dependent inhibition of the MR kinases AKT1, CDK1&2, ERBB2 and the downstream kinase EGFR markedly reduced cell viability in a large panel of human adenocarcinoma cell lines." (PMID 39995112, 2025). "Among them, ERBB2 (also known as HER2) alterations have emerged as important targets, particularly in adenocarcinomas without EGFR, ALK, or ROS1 aberrations." (PMID 41426315, 2025). "Among the unselected adenocarcinoma patients, EGFR and ERBB2 mutations and ALK fusions were frequent in nonsmoking female patients." (PMID 31387567, 2019). "For example, in the case of a patient with adenocarcinoma of the esophagogastric junction and the ERBB2 amplification, clinician feedback noted that the MTB recommendation (Trastuzumab-Deruxtecan) was based on the pathology HER2 DAKO 3+ Score, which was due to the ERBB2 Amplification." (PMID 40053768, 2025).
breast (86 papers, 2004 to 2025). "Our findings showed that ERBB2 V659/G660 mutations were detected in 0.17% of lung ADC cases and 0.4% (one out of 260) of cases with mixed ADC and SCC." (PMID 32478891, 2020). "A time-course mRNA expression analysis of the NRG1 isoforms, ErbB3 and ErbB4 receptors, and their co-receptors ErbB2 and ErbB1, was performed on SDF muscle after median nerve injury." (PMID 29568012, 2018). "Consequently, we selected eight statistically significant TACTs—EPCAM, KRT19, ERBB2, MKI67, MCAM, FOXA2, SNAI2, and NPTN—which we designated as colorectal TACTs (C-TACTs)." (PMID 40003943, 2025).
infection (78 papers, 2007 to 2026). The state of being infected such as from the introduction of a foreign agent such as serum, vaccine, antigenic substance or organism. "We also used a published anoikis-resistant derivative of MCF10A cells, MCF-ErbB2 cells, which were generated by infection of MCF10A cells with a retrovirus encoding the wild-type ErbB2." (PMID 30545388, 2018). "ERBB2, belonging to the epidermal growth factor receptor family of receptor tyrosine kinases, had also been previously linked to the cytokine release storm and thus severity of an infection with SARS-CoV-2." (PMID 35903362, 2022). "HV-HP infection attenuated the effect of EGF treatment on ERBB2 expression in N87 cells only (p<0.05)." (PMID 40642068, 2025). "As previously shown for siRNA-mediated knockdown and tucatinib treatment, our experiments support the conclusion that ErbB2 is dispensable for the initial stages of infection such as binding and entry platform formation." (PMID 38370412, 2024). "The observation that the inhibitors induced a stronger infection inhibition when added after virus entry, strongly suggests a role of ErbB2 in post entry steps such as viral gene regulation." (PMID 38370412, 2024). "This supports that ErbB2’s major role is late in the infection cascade, such as the viral gene transcription regulated by the long control region (LCR) of HPV16, which occurs after the virus has reached the host cell nucleus." (PMID 38370412, 2024). "From the ErbB family, only ErbB2 continuously increased in the time course of infection along with the virus in both keratinocyte cell systems." (PMID 38370412, 2024). "This additional feature abrogates the virus ability to enter cells through the natural receptors HVEM/Nectin-1, and enables the specific infection of cells overexpressing ERBB2 in addition to the conditional replication through Survivin/BIRC5 promoter." (PMID 32152425, 2020). "We further tested the effect of Mek on ErbB2 in detached MCF10A cells and a variant of these cells MCF-MekDD generated by infection of the former cells with the retrovirus encoding an activated Mek mutant." (PMID 29285258, 2017). "Infection with N. meningitidis strain MC58 for 2 h, however, caused enhanced re-distribution of ErbB2 to the site where bacteria had attached and formed microcolonies (first row), where we also detected ceramide-enriched platforms." (PMID 24945304, 2014). "Interestingly, ERBB2 receptor has roles in mycobacterial infections, with M. leprae directly binding ErbB2 to enter the host cells, while M. tuberculosis induced ErbB2, preventing proper macrophage function and increased infection." (PMID 40762982, 2025). "Moreover, we also found that the knockout of EGFR or ERBB2 inhibited the internalization and infection of FMDV." (PMID 38512977, 2024). "Nevertheless, one hypothesis that can be drawn from these data is that IGF1R activity is solely important early during infection, while ERBB2 has roles throughout the infection." (PMID 38585651, 2024). "In order to evaluate whether the decreased expression of erbB2 was controlled by M2 receptors directly or via the Notch-1 pathway, infection with recombinant adenovirus expressing the construct GFP-NICD was performed." (PMID 35204740, 2022). "The infection progression associated with essential epigenetic modifications in two strains of C. albicans such as ARRB2, CDH1, HSP90B1, EGFR and ERBB2, and host miRNA repressing on pathogens genes are mostly identified in core HPCNs by our systems biology approach." (PMID 30769958, 2019). "The commonly upregulated 23 genes showed Reactome enrichment of ERBB2 signaling pathways, which are part of tyrosine kinase receptors and regulate host cell entry in M. leprae; they also prevent macrophage function, leading to enhanced infection with M. tuberculosis." (PMID 40762982, 2025).
infection (continued). "Our analysis revealed stage-specific signatures: NILM displayed a "stealth infection" profile marked by upregulated protein synthesis and growth signaling (EGFR/ERBB2) alongside immune suppression." (PMID 41855211, 2026). "We observed altered levels of phosphorylated ERBB2 and IGF1R with differing kinetic patterns during infection." (PMID 38585651, 2024). "Strikingly, we observe DENV infection leads to phosphorylation of ERBB2 and IGF1R at different times during infection." (PMID 38585651, 2024). "In the infection progression of C. albicans SC5314, orf19.1816 (ALS3) plays a significant role in cell adhesion and endocytosis induction by interacting with EGFR, ERBB2 (HER2), CDH1 (E-cadherin), HSP90B1 and TJAP1 (TJP4)." (PMID 30769958, 2019). "Previous studies indicate that orf19.1816 will induce endocytosis by binding host cell receptors such as ERBB2, HSP90B1, CDH1 and CDH2 so that it will be considered as an infection initiation." (PMID 30769958, 2019). "In response to pathogen infection, the receptors such as EGFR, ERBB2, CDH1, HSP90B1, and TJAP1 at the host membrane interact with pathogen cell wall proteins to start inducing endocytosis." (PMID 30769958, 2019). "By using genotype 1b replicon cells as well as an infection-based system we found that while transcript and protein levels of EGFR and ErbB2 were up-regulated or unaffected, respectively, HCV induced a substantial reduction of ErbB3 and ErbB4 expression." (PMID 26886748, 2016). "929-B6 enabled efficient, receptor-specific transduction of ERBB2-expressing cells without increasing infection of ERBB2-negative controls." (PMID 41472234, 2025). "MSH6 expression varies among GC cell lines and showed a modest negative correlation with ERBB2 expression under HV-HP infection in the N87 cell line (t-value= –3.498, p = 0.0395)." (PMID 40642068, 2025). "TOB1-knockout inhibited the infection of FMDV, presumably through the EGFR/ERBB2 signaling pathway." (PMID 38512977, 2024). "Indeed, targeting ErbB2 reduced the phosphorylation of this receptor and its downstream signaling pathways, effectively inhibiting LCR activity and eventually infection." (PMID 38370412, 2024). "In both keratinocyte cell types, infection assays using HPV16 PsVs carrying a promoter reporter plasmid with the viral LCR as regulatory element, showed strong reduction in pseudoinfection upon ErbB2 depletion." (PMID 38370412, 2024). "To test whether reduced protein levels of EPHB4, ERBB2, FGFR2, or IGF1R impacted infection, we infected control and knockdown lines with DENV2 MON601 for 24 h." (PMID 38585651, 2024). "In addition, overexpression of miR-205-5p in BCSC #1 cells by infection with pCMV-RFP-2A-puro lentivector results in strongly reduced protein levels and in reduced mRNA levels of both ErbB2 and EGFR." (PMID 26181203, 2015). "To examine whether this receptor is recruited and trapped into ceramide-enriched membrane platforms, we compared the subcellular distribution of ErbB2 in HBMEC before and after infection with N. meningitidis." (PMID 24945304, 2014). "Furthermore, quantitative PCR (qPCR) analysis of transgenic rat Erbb2 expression in haematopoietic lineage-depleted cells from peripheral blood showed no changes with infection." (PMID 40739350, 2025). "Since T-cells and monocytes/macrophages are the primary cell types to be infected at the portal of entry in vivo, the HIV-infected T-cells may induce ERBB2 and other PTK-related pathways soon after infection and VEGF-independent pathways may possibly precede HIV-infection of endothelial cells." (PMID 19712456, 2009). "A trend toward reduced ErbB2 levels, albeit statistically nonsignificant, was also measured at the early time point after infection, whereas the level of cell surface NRP1 was increased upon infection." (PMID 37581931, 2023).
infection (continued). "Contrariwise, in the absence of human ERBB2 expression, the infection of wild-type LLC1 cells by SurE_oHSV was completely abrogated, while the same cells were still permissive to R-LM55 and Survivin_oHSV infection." (PMID 32152425, 2020). "We first checked the transcription of these ErbB members by real-time PCR and found that the transcription levels of EGFR, ErbB2, and ErbB4 did not significantly change in response to SC19 infection, while ErbB3 showed a significant decrease since 2 h post infection." (PMID 27756321, 2016).
gastrointestinal tumors (31 papers, 2007 to 2026). "In this study, ERBB2-mutant gastrointestinal tumors (EAC, GC, and CRC) were classified into three groups." (PMID 37754252, 2023). "In the future, treatment methods may be tailored to the biological features of ERBB2-mutant tumors, and such classification may contribute to the development of more effective therapies for ERBB2-mutant gastrointestinal tumors." (PMID 37754252, 2023). "However, no effective treatment has been established for gastrointestinal tumors targeting ERBB2 mutations." (PMID 37754252, 2023). "Notably, copy number changes for ERBB2 have been shown to strongly correlate with overexpression levels detected by IHC, and actionable ERBB2 mutations are now commonly included in NGS panels for CGP of gastrointestinal tumors." (PMID 38138928, 2023).